CDK1 (cyclin dependent kinase 1)
Diseases named in the same sentence as CDK1 in open-access papers (continued):
Sharing a sentence is not in itself a finding about the gene and the disease.
breast cancer (continued). "Interestingly, some genes involved in these processes and signal pathways, such as CCNB1, CDK1, CHEK2, and MYBL2, have been widely reported as oncogenes and used in the clinical diagnosis for breast cancer patients." (PMID 34646403, 2021). "Further analysis demonstrated that the expression of cell cycle-related genes (CDC6, CDC25A, CDK1, ATM, E2F1, and MKI67) were much higher in breast cancer patients of 3 target genes high expression group or MIR3613 deletion group compared with their counterpart, respectively." (PMID 33494814, 2021). "However, almost all interactions of CDK1 and those of SKP1 with CDK1 neighboring proteins were breast cancer-exclusive." (PMID 33670716, 2021). "VIRMA can facilitate breast cancer by regulating CDK1 mRNA expression without changing the m6A modification in CDK1." (PMID 34315512, 2021). "Nevertheless, whether these drugs could exert therapeutic effects on breast cancer by inhibiting the over-expression of RRM2, CDK1 and CCNA2, or whether CCNB2, BUB1B and CDC20 are promising therapeutic targets still need to be supported by further research." (PMID 33083112, 2020). "Importantly, the differential expression of the selected proteins reflects key clinical parameters defining breast cancer subtypes: ER status (INPP4B); tumor grade (CDK1); and HER2 status (ERBB2)." (PMID 31315058, 2019). "Taken together, these data suggest that CDK1 and CDK2 may serve as potential biomarkers for predicting the outcome of cancer patients, especially those with breast cancer." (PMID 31428132, 2019). "In accord with these results, breast cancer gene array profiling indicated that elevated expression of KLF4 in both MCF10A and MCF7 breast cancer cell lines upregulates transcription of several oncogenes and cell cycle activators such as MAPK, EGF/EGFR, IGF1, CYCLIN D2, CDK1, and CYCLIN E1." (PMID 30613353, 2018). "The effects of treatment with Sepin-1 that are similar on the four breast cancer cell lines include non-activation of caspases 3 and 7 and downregulation of cell cycle-driving proteins, such as Raf, FoxM1, Plk1, Cdk1, Aurora A, Lamin B1, and pericentrin." (PMID 29780443, 2018). "Thus, inhibition of both CDK1 and CDK12 by Dinaciclib seems to be important in the reversal of chemoresistance in breast cancer cells." (PMID 29686231, 2018). "MAD2L1, CDK1 and ACACB exhibit significantly distinctive expression patterns and may be highly involved in cacer related pathways of breast cancer, DCIS." (PMID 28977921, 2017). "Thus, the potential function of CDK1 inhibition on EMT and breast cancer metastasis warrants further investigation." (PMID 28067227, 2017). "Selective inhibition of cdk1 function by small molecules such as RO-3306 is feasible and cdk1 inhibition had synergistic effects in combination with PARP inhibition in preclinical models of breast cancer." (PMID 26029996, 2015). "A control CDK1-selective inhibitor, bohemine, showed pronounced inhibition of proliferation of both cell types; however, the VEGFR-specific inhibitor vatalanib did not significantly inhibit cell proliferation in endothelial cells or breast cancer cells." (PMID 25393739, 2014). "SiRNA-mediated CDK1 depletion significantly reduced cell viability in the three MYC-dependent breast cancer cell lines AU565, SKBR3 and BT549, but did not affect cell viability of the MYC-independent cell line MDA-MB-175." (PMID 24444383, 2014). "We found that targeting CDK1 rather than CDK4/6 or CDK2 selectively reduced the viability of MYC- dependent breast cancer cells, suggesting a potential therapeutic value of targeting CDK1 for MYC-driven human breast cancer." (PMID 24444383, 2014). "The treatment of HER-2/neu-overexpressing breast cancer cells with AC downregulated Cdk4 without altering the Cdk1/2 protein." (PMID 22701509, 2012).
breast cancer (continued). "CDK1 has been reported as an Hsp90α interactor that was observed to be degraded in response to Hsp90 inhibition, and there is evidence that it may be a valuable CDK target in breast cancer." (PMID 40714319, 2025). "Previous research has revealed that CDK1 is present in the cell cycle of numerous tumor-regulating cell adhesions and may served as a potential biomarker for non-small-cell lung cancer(NSCLC), CRC, breast cancer, and ovarian cancer." (PMID 38485838, 2024). "Disorders in cell-cycle-related pathways have key influences on breast cancer prognosis, and our feature selection result highlights that CDK1, CDK4, AURKA, and PLK1 may play vital roles in the complex cell cycle regulatory network, which in turn affects breast cancer prognosis." (PMID 34290286, 2021). "CDC20, CDK1, and PLK1 may be the targets of podophyllotoxin in breast cancer." (PMID 32848800, 2020). "As the result of luminal breast carcinomas, Securin (HR 1.1, p = 0.02, CI 1.0–1.2) and nuclear Separase (HR 5.7, p = 0.002, CI 1.9–17.2) – but not Cdk1 remained the most powerful predictors of cancer mortality, along with nodal status (HR 4.9, p = 0.003, CI 1.7–13.7)." (PMID 32546141, 2020). "Moreover, six hub genes were selected and validated in clinical sample for further analysis owing to the high degree of connectivity, including CDK1, CCNA2, TOP2A, CCNB1, KIF11, and MELK, and they were all correlated to worse overall survival (OS) in breast cancer." (PMID 31428132, 2019). "Combined CDK1 and CDK2 depletion caused massive reduction in colony formation in all cell lines, suggesting that small-molecule inhibition of CDK1 and CDK2 may be an effective strategy for treatment of both anti-estrogen-sensitive and resistant breast cancer populations." (PMID 20010939, 2010). "Notably, although proliferative TAMs have been identified by proliferation indicator Ki-67 (MKI67) and cell cycle genes such as CDK1 in various cancer models, such TAMs were not previously identified in breast cancer due to various gene expression across cancer types." (PMID 39232806, 2024). "Unlike CCNB1, CCNA2, and CDK1, currently, the remaining genes (TOP2A, KIF11, and MELK) are not found to be associated with cell cycle; their dysfunctions might still affect the progression and prognosis of breast cancer." (PMID 31428132, 2019). "The different sensitivity did not appear to be related to CDK1 expression, since CDK1 expression did not vary markedly between the cell lines used here, consistent with previous data showing that there are not large variations in CDK1 expression in breast cancer cell lines." (PMID 24444383, 2014). "We first compared the CDK1 and Cyclin B1 protein levels in several common TNBC cell lines (MDA-MB-231, MDA-MB-468, HCC1937, and SUM149PT) and non-TNBC breast cancer cell lines (T47D and MCF-7) with those in 293 cells and normal HDFs." (PMID 32575711, 2020). "ZNF695 was also shown to upregulate cell cycle progression genes (e.g., CDK1, PLK1) cooperatively with other master regulators in nonluminal breast cancers." (PMID 30444046, 2019). "Selective targeting of CDK1, rather than CDK4/6 or CDK2, may exert lethal effects on MYC-dependent breast cancer cells." (PMID 41142571, 2025). "Notably, CDK1, CCNA2, P4HA1, PAICS, and RAD51 showed a CERES score higher than zero in most breast cancer cell lines, indicating that they might not be essential to breast cancer." (PMID 34745136, 2021).
lung cancer (126 papers, 2011 to 2026). A malignant neoplasm involving the lung. "The Cancer Genome Atlas (TCGA) analysis of lung cancers indicated that CDK1 and KIF family member overexpression was associated with an unfavorable survival." (PMID 40232858, 2025). "Upregulation of CDK1 is associated with decreased survival time of patients with multiple cancer types, including colorectal, liver, and lung cancer." (PMID 38002302, 2023). "CDK1 was associated with maintenance of stem cell properties in lung cancer by interacting with SOX2, another stem cell marker in CRC, and its protein expression increases significantly from normal mucosa to dysplasia and from dysplasia to carcinoma." (PMID 36362041, 2022). "Based on mouse and human models, CDK1 was found strongly associated with the progression of lung cancer and suggested as a potential prognostic biomarker." (PMID 34650921, 2021). "Different from our findings, Zhang C found loss of cytoplasmic CDK1 predicts poor survival in human lung cancer." (PMID 33758599, 2021). "To date, accumulating evidence has elucidated that CDK1 is significantly overexpressed and associated with poor outcome in gastric and lung cancers." (PMID 32537471, 2020). "A high expression of CDK1 is negatively associated with overall survival for lung cancer, HCC, epithelial ovarian cancer, and pancreatic ductal adenocarcinoma." (PMID 32596342, 2020). "Some references have shown that the abnormal expression of CDK1 was associated with poor prognosis of some other cancers including colorectal cancer, lung cancer, and pleural mesothelioma." (PMID 33365314, 2020). "CDK1 overexpression has been documented in lymphoma, advanced melanoma and lung cancer, and loss of cytoplasmic CDK1 predicts poor survival and confers chemotherapeutic resistance in the latter." (PMID 25625291, 2015). "Dysregulation of CDK1 causes rapid tumor growth and spontaneous proliferation of cancer cells, emphasizing that high gene expression levels of CDK1 are involved in the progression of multiple cancer types, including colorectal, liver, and lung cancer." (PMID 38002302, 2023). "Previous studies proved that CDK1 was a diagnosis biomarker for several cancers; we predicted the diagnostic value of CDK1 in renal cancer, liver cancer, pancreatic cancer, and lung cancer from online database; the results showed that CDK1 was a good prognostic biomarker (P < 0.01)." (PMID 35601741, 2022). "CDK1 overexpression has been documented in lung cancer, lymphoma, and advanced melanoma, while loss of cytoplasmic CDK1 predicts poor patient survival and may confer chemotherapeutic resistance in the latter." (PMID 32093341, 2020). "Loss of cytoplasmic CDK1 could predict poor survival in human lung cancer and confers chemotherapeutic resistance." (PMID 32426332, 2020). "CDK1 may be associated with the malignant phenotype of lung cancer." (PMID 40167359, 2025). "Experimental evidence suggests that CASC11 facilitates the progression of lung cancer by interacting with microRNA-302, increasing the expression of CDK1." (PMID 40303981, 2025). "Survival analysis revealed that overexpression of CDK1, PLK1, AURKA, KIFC1, and KIF2C was associated with a statistically significant unfavorable overall survival in patients with lung cancer." (PMID 40232858, 2025). "In lung cancer, CDK1 is upregulated compared with normal tissues and was negatively correlated with the overall survival of lung cancer patients." (PMID 40040723, 2025). "Examples include BAP1 in cervical and lung cancer, CDK1 in bladder cancer, E2F2 in ovarian cancer, and RHOA, VEGF, NUMB, among others, in oral cancer." (PMID 41373532, 2025). "For example, elevated CDK1 transcript and protein levels have been observed in lung cancer samples compared to normal tissue." (PMID 40167359, 2025). "RNA-Seq analyses after CDK2 inhibition of 4N versus 2N lung cancer cells were enriched for CDK1 pathway and KIF family members." (PMID 40232858, 2025).
lung cancer (continued). "Dinaciclib has been previously shown to induce anaphase catastrophe in lung cancer cells through suppression of CDK1 and CDK2." (PMID 41080754, 2025). "Gastrodin inhibits lung cancer cells resistant to pemetrexed by promoting survivin degradation through the inhibition of the Akt/WEE1/CDK1 signaling pathway." (PMID 39468027, 2024). "CDK1 is a potential prognostic biomarker and target for lung cancer; CDK1 activity is critical for JAK/STAT3 signaling activation, and the inhibition of CDK1 can suppress lung cancer." (PMID 38783288, 2024). "The cyclin-dependent kinase (CDK) family includes 20 different types of enzymes (CDK1-20), which have been proven to play a crucial role in various types of cancer, including melanoma and lung cancer, as oncogenes." (PMID 38370368, 2024). "Overall, these results suggest that CDK1 down-regulation by indomethacin in lung cancer cells leads to a decrease in nucleolin levels and ultimately increases SSAT-1." (PMID 37759783, 2023). "Previous studies have shown that silencing CircIGF1R protects against neuronal injury, regulates psoriasis via miR-194-5p/CDK1, and inhibits cell invasion and migration in lung cancer." (PMID 36835196, 2023). "Combined with the results of this study, it can be inferred that CHEK1, CCNB1, CCNB2, and CDK1 are critical genes involved in cell cycle arrest and DNA damage repair in lung cancer." (PMID 36714024, 2023). "The microarray datasets GSE7670, GSE151102, GSE33532, GSE43458, and GSE19804 were further analyzed to determine the accuracy and reliability of the related expression of the four essential core genes (CHEK1, CCNB1, CCNB2, and CDK1) in lung cancer." (PMID 36714024, 2023). "CDK1 and CDK12 inhibition led to HR deficiency by decreasing HR repair proteins RAD51, BRCA1, and BRCA2 in lung cancer." (PMID 37370140, 2023). "Kaplan–Meier plotter was used to analyze the prognosis of the core genes CHEK1, CCNB1, CCNB2, and CDK1 in patients with lung cancer." (PMID 36714024, 2023). "Recent studies have demonstrated that interaction and phosphorylation of SOX2 by CDK1 positively regulate stemness in lung cancer, and CDK1 phosphorylation of both HIF-1α and EZH2 promotes tumor cells survival and proliferation." (PMID 37189841, 2023). "CHEK1, CCNB1, CCNB2, and CDK1 are the critical core genes of lung cancer and are highly expressed in lung cancer." (PMID 36714024, 2023). "GEPIA online software was used to analyze the expression of CHEK1, CCNB1, CCNB2, and CDK1 in 969 lung cancer tissues (including lung adenocarcinoma and lung squamous cell carcinoma) and 685 normal lung tissues." (PMID 36714024, 2023). "Overexpression of CDK1 in lung cancer reduces chemosensitivity and is related to the lower survival rate of patients." (PMID 36714024, 2023). "TRIM59 has a high expression level in a variety of lung cancer cell lines, while knockdown of which can affect the expression of cyclins (including CDC25C and CDK1), thereby enhancing the proliferative and migratory abilities of lung cancer cells." (PMID 35912155, 2022). "Our results indicated that VLX1570 arrested the cell cycle at G2/M phase through promoting the degradation of CyclinB1 and CDK1 in lung cancer cells." (PMID 34854221, 2022). "We analyzed lung cancer cohorts with KRAS mutations (GSE31210) and found that higher hub gene levels (BUB1, BUB1B, NCAPG, CDC20, CDK1, KIF11) were significantly associated with worse OS in lung cancer patients with KRAS mutations." (PMID 36176446, 2022). "Our results are consistent with data from other groups, which reveal that CDK1 promotes the migration of lung cancer cells and colorectal cancer cells via different mechanisms." (PMID 35806389, 2022). "Despite of these, the mechanistic study in our study identified CDK1 as a potential downstream target of NLE1 in the regulation of lung cancer." (PMID 36818671, 2022).
lung cancer (continued). "There was a significant upregulation of CDK1 gene expression in lung cancer tissues than in normal tissues, and the results from the TCGA dataset showed a fold change of 6.939 (P=4.26E − 24)." (PMID 36090896, 2022). "In parallel, in the lung, Bcl-2/Bax and lung cancer-related factors CDK1, CDC20, P38α etc were significantly increased in stress+smoke group." (PMID 36417428, 2022). "For example, CDK1 positively regulated the stemness of lung cancer cells and mediated the signaling for proliferation, invasion, and migration in NSCLC cells." (PMID 35805937, 2022). "CDC20 together with CENPA, CDK1, AURKA, and TPX2 were also diagnostic biomarkers in LUAD, and elevated mRNA levels of CDC20 were correlated with poor prognosis of lung cancer." (PMID 34650921, 2021). "(2020) analyzed the prognostic value of CDK1 mRNA expression in lung cancer patients using KM plotter." (PMID 34586751, 2021). "CDK1 was also found to be the hub gene in other kinds of cancers, such as cervical cancer and lung cancer 36-38." (PMID 33758599, 2021). "MiR-181a hinders lung cancer cell proliferation and migration by targeting CDK1 (cyclin dependent kinase 1) and KRAS." (PMID 32318335, 2020). "In line with the findings in our study, CDK1 is overexpressed in several cancer types, including laryngeal squamous cell carcinoma, lung cancer, HCC, epithelial ovarian cancer, and pancreatic ductal adenocarcinoma." (PMID 32596342, 2020). "CDK1 was reported to regulate the development of lung cancer by interacting with LncRNA, miRNA and circRNA." (PMID 33308216, 2020). "Previous studies have shown that CDK1 is involved in the progression of multiple types of cancer, including colorectal cancer, liver cancer, and lung cancer." (PMID 32127012, 2020). "Altogether, the present results suggest a potential preventive and treatment strategy for lung cancer via suppression of GP130/STAT3 signaling via CDK1 inhibition or iron deprivation." (PMID 30931929, 2019). "FSTL1 inhibition induced the cellular portion of G2/M phase in human lung cancer cells via the accumulation of regulators of the transition through the G2/M phase, including the cyclin-dependent kinase 1 (Cdk1)-cyclin B1 complex." (PMID 26716515, 2016). "Previous studies have demonstrated that decreased phospho-Cdk1 (Thr161) expression, as well as the accumulation of phospho-Cdk1 (Tyr15), are involved in G2/M arrest and apoptosis in lung cancer, thus validating Cdk1 as a possible therapeutic target." (PMID 25663895, 2015). "In summary, miR-129 suppressed lung cancer cell proliferation by arresting cell cycle at G2/M phase through inactivation of CDK1 by Wee1, and reduced cell migration and invasion in lung cancer through controlling the protein levels of NF-κB and MMP-2." (PMID 26081366, 2015). "Our chemotherapy experiments demonstrate that lowering total levels of CDK1 or cytoplasmic levels of CDK1 confers chemotherapeutic resistance to many agents used to treat lung cancer, especially microtubule-directed agents." (PMID 21887332, 2011). "For example, in lung cancer, overexpression of CDK1 is suggestive of a dismal prognosis." (PMID 40748969, 2025). "Furthermore, it has been demonstrated that the CDK1/Sox2 axis acts as an important axis in the control and maintenance of the stemness of lung cancer cells, and inhibiting CDK1 increases the sensitivity of lung cancer to chemotherapeutics." (PMID 39820173, 2025). "Furthermore, the combined application of miR-506 and miR-143 in the treatment of lung cancer LC and PC synergistically downregulates CDK1, CDK4, and CDK6, blocking both the G1/S and G2/M transitions and inducing robust apoptotic activity." (PMID 40248198, 2025).